EVI2A (ecotropic viral integration site 2A)
Description:
May complex with itself or/and other proteins within the membrane, to function as part of a cell-surface receptor.
Synonyms: EVI-2A; EVDA; EVI2
Tractability: Antibody: its Gene Ontology location is reachable by antibodies, with high confidence; UniProt predicts a signal peptide or a membrane-spanning region; the Human Protein Atlas places it where antibodies can reach. PROTAC: ubiquitination databases record sites on it.
Gene: Protein-coding gene on chromosome 17 (31,316,410 to 31,321,749, reverse strand). Ensembl gene ENSG00000126860.
Subcellular location: Membrane
Subcellular location (Human Protein Atlas): Golgi apparatus; Plasma membrane; Primary cilium; Vesicles; Cytosol; Primary cilium transition zone
Gene Ontology:
Molecular function: protein binding; transmembrane signaling receptor activity
Cellular component: plasma membrane; membrane
Genetic constraint (gnomAD): Loss-of-function variants: 12 observed, 14.99 expected, observed/expected ratio (o/e) 0.8, 90% interval 0.51 to 1.3. The upper end of that interval is the gene's LOEUF score, 1.3, which puts it in group 5 of 6, group 1 being the genes least tolerant of losing a copy. Missense variants: 267 observed, 293.72 expected, observed/expected ratio (o/e) 0.91, 90% interval 0.82 to 1.01. Synonymous variants: 89 observed, 103.11 expected, observed/expected ratio (o/e) 0.86, 90% interval 0.73 to 1.03.
Homologues: Orthologues: chimpanzee EVI2A (99% identical), macaque EVI2A (95% identical), pig EVI2A (79% identical), guinea pig EVI2A (78% identical), rabbit EVI2A (74% identical), dog EVI2A (73% identical), rat Evi2a (65% identical), mouse Evi2a (62% identical).
Diseases named in the same sentence as EVI2A in open-access papers:
EVI2A is named in the same sentence as 23 diseases in open-access papers, as found by Europe PMC text mining. Sharing a sentence is not in itself a finding about the gene and the disease. The quoted sentences say what the papers report.
head and neck squamous cell carcinoma (2 papers, 2020 to 2024). A squamous cell carcinoma that arises from any of the following anatomic sites: lip and oral cavity, nasal cavity, paranasal sinuses, pharynx, larynx, and salivary glands. "EVI2A hypomethylation may be associated with head and neck squamous cell carcinomas." (PMID 32633782, 2020). "Our pan-cancer analysis unveiled a conspicuous upregulation of EVI2A expression not only in KIRC but also in other malignancies such as breast cancer (BRCA), Head and Neck Squamous Cell Carcinoma (HNSC), Cholangiocarcinoma (CHOL), and Kidney Renal Papillary Cell Carcinoma (KIRP)." (PMID 39449801, 2024).
diabetes (1 paper, 2021). "PheWAS analysis of the eight candidate susceptibility genes revealed that four candidate genes (CYP19A1, EIF2AK4, EVI2A and SNX11) associated with 56 traits related to seven phenotypic categories: anthropometric, bone health, cardiovascular, diabetes, hematopoiesis, liver function, and sex hormones." (PMID 34675350, 2021).
endometrial cancer (1 paper, 2021). Primary or metastatic malignant neoplasm involving the endometrium (mucous membrane that lines the endometrial cavity). "The associations of CYP19A1, SKAP1, HEY2, EEFSEC, and EVI2A were supported by colocalization of eQTL and GWAS signals in at least one of the relevant tissues; thus, these five genes were prioritized as candidate endometrial cancer susceptibility genes." (PMID 34675350, 2021).
head and neck cancer (1 paper, 2020). A primary or metastatic malignant neoplasm affecting the head and neck. "On the other hand, EVI2A has been confirmed to be involved in lymphocyte proliferation and viability, which is a well-defined immune-specific tumor suppressor in head and neck cancer." (PMID 32904067, 2020).
kidney cancer (1 paper, 2024). Primary or metastatic malignant neoplasm involving the kidney. "In summary, these findings unequivocally underscore the indispensable role of EVI2A in governing the viability, migration, and survival of kidney cancer cells." (PMID 39449801, 2024). "Our results indicated that suppressing the expression of EVI2A impedes kidney cancer cells’ growth, spread, and mobility, aligning with our previous bioinformatics predictions." (PMID 39449801, 2024).
leukemia (1 paper, 2024). A malignant (clonal) hematologic disorder, involving hematopoietic stem cells and characterized by the presence of primitive or atypical myeloid or lymphoid cells in the bone marrow and the blood. "Recurrent copy number alterations (CNAs) were identified in genes related to leukemia and hematopoiesis, among which deletions of a region containing NF1, EVI2A and EVI12B were particularly frequent (n = 6)." (PMID 38972954, 2024).
Obesity (1 paper, 2018). Accumulation of substantial excess body fat. "In our previous study, we reported that 14 adipocyte genes (Ccl7, Emr1, Evi2a, Gusb, H2-DMb2, Lcp1, LOC100041137, Ly9, Ptpre, Rgs1, sc1000528.1_16, Sirpa, Sfrp5, and Acacb) were associated with both advanced age and diet-induced obesity." (PMID 30282902, 2018).
renal carcinoma (1 paper, 2024). A carcinoma arising from the epithelium of the renal parenchyma or the renal pelvis. "The Western blotting (WB) and RT-qPCR results from 10 pairs of renal cancer and adjacent tissues indicate elevated EVI2A expression in renal cancer tissues." (PMID 39449801, 2024). "Furthermore, we substantiated that EVI2A exerts a discernible impact on renal cancer cell function through meticulously designed in vitro experiments." (PMID 39449801, 2024).
renal cell carcinoma (1 paper, 2024). "Furthermore, the discernible involvement of EVI2A in the immune microenvironment of renal cell carcinoma unveils novel perspectives that could significantly impact the landscape of immunotherapeutic approaches for this disease." (PMID 39449801, 2024).
renal clear cell carcinoma (1 paper, 2024). "In summary, EVI2A holds the potential to emerge as a target in future treatments for renal clear cell carcinoma." (PMID 39449801, 2024). "Our investigation has pinpointed EVI2A as a novel molecular marker for renal clear cell carcinoma, identified through meticulous analysis of the TCGA database." (PMID 39449801, 2024). "Analysis of data from the GEO and TCGA databases revealed an upregulation of EVI2A expression in renal clear cell carcinoma tissues compared to adjacent normal tissues." (PMID 39449801, 2024). "Additionally, in vitro experiments consistently validated the heightened expression of EVI2A in renal clear cell carcinoma cells compared to normal kidney cells." (PMID 39449801, 2024).
viral meningitis (1 paper, 2024). Inflammation of the membranes surrounding the brain and spinal cord due to a viral infection. "In viral meningitis subjects, the ceRNA network was composed of hsa-miR-199b-5p, 4 mRNAs (ANKRD22, EVI2A, USP15, and C8orf88), and AC002511.1." (PMID 38347610, 2024).
tumor (5 papers, 2014 to 2024). "Initially, we leveraged three datasets (KIRC_GSE111360, KIRC_GSE139555, and KIRC_GSE145281_aPDL1) from the TISCH database to evaluate EVI2A expression within Tumor Microenvironment (TME)-associated immune cells." (PMID 39449801, 2024). "Research findings have illuminated the overexpression of Ecotropic Viral Integration Site 2A (EVI2A) in certain neoplasms, positioning it as a promising prognostic marker." (PMID 39449801, 2024). "This study will contribute to a more profound comprehension of the potential role of EVI2A in tumor pathogenesis." (PMID 39449801, 2024). "It is possible that Evi2a is a lymphocyte-specific tumor suppressor, which could play a role in BCR activation." (PMID 37244954, 2023). "Hence, it is possible that Evi2a is a lymphocyte-specific tumor suppressor." (PMID 24706754, 2014). "Our results indicate that EVI2A expression is upregulated in KIRC, showing correlations with tumor grade and T/N/M stage." (PMID 39449801, 2024). "A statistically significant elevation of EVI2A expression in KIRC was observed when comparing tumor and normal tissue samples, a trend further substantiated by the results from paired samples." (PMID 39449801, 2024).
cancer (4 papers, 2019 to 2024). A tumor composed of atypical neoplastic, often pleomorphic cells that invade other tissues. "The outcomes underscored the close association of EVI2A with various immune-related pathways, including immunoglobulin receptor binding, PD-L1 expression, PD-1 checkpoint pathway in cancer, and the T cell receptor signaling pathway." (PMID 39449801, 2024). "The findings from The Cancer Immunome Atlas (TCIA) align with this correlation, demonstrating that when at least one of CTLA-4 or PD-1 is positive, high expression of EVI2A is associated with increased sensitivity to immunotherapy." (PMID 39449801, 2024). "Of the 9 coding genes and one other lncRNA in this locus, expression of AC138207.5 is significantly correlated with ADAP2 in all five cancer types, and with EVI2A/B in most of the five cancer types." (PMID 30767760, 2019).
EVI2A also shares sentences with these, for which no sentence is quoted: breast carcinoma (1 paper); cholangiocarcinoma (1); developmental delay (1); germinoma (1); melanoma (1); microdeletion syndrome (1); neurofibroma (1); neurofibromatosis type 1 (1); osteosarcoma (1); schizophrenia (1).